ADAM2 (ADAM metallopeptidase domain 2)
Description:
Sperm surface membrane protein that may be involved in sperm-egg plasma membrane adhesion and fusion during fertilization. Could have a direct role in sperm-zona binding or migration of sperm from the uterus into the oviduct. Interactions with egg membrane could be mediated via binding between its disintegrin-like domain to one or more integrins receptors on the egg. This is a non catalytic metalloprotease-like protein.
Synonyms: CT15; PH30; FTNB; PH-30b; CRYN1; CRYN2; PH30-beta
Tractability: Antibody: its Gene Ontology location is reachable by antibodies, with high confidence; UniProt predicts a signal peptide or a membrane-spanning region.
Gene: Protein-coding gene on chromosome 8 (39,743,735 to 39,838,227, reverse strand). Ensembl gene ENSG00000104755.
Subcellular location: Membrane
Pathways (Reactome):
Reproduction: Interaction With Cumulus Cells And The Zona Pellucida
Gene Ontology:
Molecular function: integrin binding; metalloendopeptidase activity; metallopeptidase activity
Biological process: binding of sperm to zona pellucida; cell adhesion; fusion of sperm to egg plasma membrane involved in single fertilization; male gonad development; proteolysis
Cellular component: plasma membrane; cell surface; membrane; protein-containing complex
Genetic constraint (gnomAD): Loss-of-function variants: 34 observed, 38.11 expected, observed/expected ratio (o/e) 0.89, 90% interval 0.68 to 1.19. The upper end of that interval is the gene's LOEUF score, 1.19, which puts it in group 5 of 6, group 1 being the genes least tolerant of losing a copy. Missense variants: 425 observed, 425.83 expected, observed/expected ratio (o/e) 1, 90% interval 0.92 to 1.08. Synonymous variants: 164 observed, 139.23 expected, observed/expected ratio (o/e) 1.18, 90% interval 1.04 to 1.34.
Homologues: Orthologues: chimpanzee ADAM2 (98% identical), macaque ADAM2 (91% identical), pig ADAM2 (68% identical), rabbit ADAM2 (66% identical), dog ADAM2 (64% identical), rat Adam2 (60% identical), mouse Adam2 (59% identical), guinea pig ADAM2 (56% identical), zebrafish adam9b (30% identical), tropical clawed frog XB990656 (28% identical), Caenorhabditis elegans unc-71 (23% identical), Drosophila melanogaster mmd (19% identical), and 4 more. Paralogues in human: ADAM32 (41% identical), ADAM18 (40% identical), ADAM9 (33% identical), ADAM30 (30% identical), ADAM21 (27% identical), ADAM20 (27% identical), ADAM12 (27% identical), ADAM29 (26% identical), ADAM33 (26% identical), ADAM19 (25% identical), ADAM28 (25% identical), ADAM8 (24% identical), and 8 more.
Diseases named in the same sentence as ADAM2 in open-access papers:
ADAM2 is named in the same sentence as 11 diseases in open-access papers, as found by Europe PMC text mining. Sharing a sentence is not in itself a finding about the gene and the disease. The quoted sentences say what the papers report.
lung carcinoma (3 papers, 2015 to 2024). "Here the authors perform in vivo CRISPR/Cas9 loss-of-function screens in mouse lung cancer models, revealing Serpinb9 and Adam2 as regulators of immunotherapy response." (PMID 37258521, 2023). "Together, these data show that ADAM2 is a cancer-testis antigen expressed in a wide variety of tumor tissues, including a high proportion of human lung cancers, and profoundly affects the tumor immune microenvironment with implications for immune therapy." (PMID 37258521, 2023). "These transcriptional changes are virtually identical to the changes observed in our mouse lung cancer LLC model with constitutive overexpression of Adam2, further supporting our findings." (PMID 37258521, 2023). "We first evaluated expression of Adam2 in our mouse lung cancer models." (PMID 37258521, 2023). "In a lung cancer mouse model, introducing sgRNA alongside ACT revealed the testicular cancer antigen ADAM Metallopeptidase Domain 2 (ADAM2) as an immune modulator." (PMID 39538305, 2024). "We used a set of previously uncharacterized antibodies against the cancer/testis antigens ADAM2, CALR3 and SAGE1 to investigate their expression in a large panel of normal tissues as well as breast and lung cancers." (PMID 26252478, 2015). "In lung cancer, 71/510 (13.9%) of LUAD and 26/498 (5.2%) of LUSC tumors showed ADAM2 expression and ~50% of these cases showed ADAM2 amplifications, indicating that ADAM2 amplification correlates with ADAM2 expression." (PMID 37258521, 2023). "To this end, we have identified antibodies suitable for immunostaining of the three novel CT antigens ADAM2, CALR3 and SAGE1, and characterized the expression of these proteins in normal tissues and the two most common types of human malignancies, breast and lung cancer." (PMID 26252478, 2015). "Our results suggest that ADAM2, CALR3 and SAGE1 cancer/testis antigens are not promising targets for immunotherapy of breast and lung cancer." (PMID 26252478, 2015). "Surprisingly, we detected no ADAM2, CALR3 and SAGE1 in the 67 lung cancers (mainly non-small lung cancer) and 189 breast cancers, while MAGE-A proteins were present in 15% and 7–16% of these tumor types, respectively." (PMID 26252478, 2015).
male infertility (2 papers, 2019 to 2021). The inability of the male to effect fertilization of an ovum after a specified period of unprotected intercourse. "Some models resulted in male infertility with severe defects in spermatogenesis, spermiogenesis and sperm maturation, or infertility with no apparent defects in motility, morphology, and sperm count (Ace, Adam2, and Adam3)." (PMID 30429210, 2019).
bladder cancer (1 paper, 2016). "Moreover, the nearby genes pattern displayed that overexpressing ADAM2 and C8orf4 are cis-regulated by lncRNA RP11-359E19.2, involving in progression of bladder cancer." (PMID 27363013, 2016).
breast carcinoma (1 paper, 2015). "Analysis of ADAM2, CALR3 and MAGE-A expression in cohort 2 consisting of 121 breast cancers of different receptor status." (PMID 26252478, 2015). "Analysis of ADAM2, CALR3, SAGE1 and MAGE-A expression in cohort 1 consistent of 68 breast cancers of different clinical stages." (PMID 26252478, 2015). "In this study, we investigated the expression of the cancer/testis antigens ADAM2, CALR3 and SAGE1 in lung and breast cancer, the two most frequent human cancers, with the purpose of providing novel therapeutic targets for these diseases." (PMID 26252478, 2015). "We investigated the potential of three previously uncharacterized CT antigens, ADAM2, CALR3 and SAGE1, as targets for treatment of lung and breast cancer." (PMID 26252478, 2015). "In conclusion, ADAM2, CALR3 and SAGE1 should not be considered targets for treatment of lung and breast cancer." (PMID 26252478, 2015).
lung adenocarcinoma (1 paper, 2023). A carcinoma that arises from the lung and is characterized by the presence of malignant glandular epithelial cells. "In addition, ADAM2-expressing human LUAD also exhibited increased expression of E2F, G2M and MYC, targets known to accelarate lung adenocarcinoma progression." (PMID 37258521, 2023).
tumor (6 papers, 2015 to 2024). "While performing a CRISPR screen on a mouse model of lung cancer, Dubrot's team identified the immune regulator Adam2 as a cancer antigen that inhibits tumour antigen presentation and suppresses interferon expression." (PMID 39427211, 2024). "In contrast, we observed increased interferon and cytokine profiles and increased CD8 T cells in Adam2 knockout tumors concomitant with reduced tumor growth." (PMID 37258521, 2023). "Our results indicate that Adam2-mediated reduction of IFNγ signaling facilitates tumor growth primarily through downregulation of pathways associated with antigen presentation and overall activation of endogenous antitumor T-cell responses." (PMID 37258521, 2023). "We examined untreated or ACT-treated lung tumors from KrasG12D;Cas9 and BrafV600E;Cas9 mice using probes against Adam2 as well as against eGFP to detect tumor cells." (PMID 37258521, 2023). "Collectively, these data show that Adam2 functions as a tumor promoter in KrasG12D tumors but is required for cytotoxicity of adaptively transferred T cells." (PMID 37258521, 2023). "Taken together, these data reveal functions of Adam2 in the reprogramming of the tumor cells and TME to augment the cytotoxicity of antigen-specific T cells." (PMID 37258521, 2023). "Overexpression of Adam2 resulted in a dramatically faster tumor growth and significantly reduced survival compared to control cells." (PMID 37258521, 2023). "Using loss- and gain-of-function experiments, we show that ADAM2 functions as an oncogene by restraining interferon and TNF cytokine signaling causing reduced presentation of tumor-associated antigens." (PMID 37258521, 2023). "As such, Adam2 expression and the associated decreased IFN signaling appears to result in a less exhausted tumor microenvironment, which is highly permissive to ex vivo expanded, adoptively transferred cytotoxic T cells or rejuvenated endogenous cytotoxic T cells." (PMID 37258521, 2023). "Interestingly, in the presence of activated exogenous tumor-specific CD8 T cells, Adam2 expression results in increased tumor clearance by enhanced cytotoxicity of adoptively transferred CD8 T cells." (PMID 37258521, 2023). "In addition, combining PDL1 or CTLA4 inhibition with ACT led to almost complete tumor stasis of Adam2 overexpressing and control tumors, indicating strong cooperative effects." (PMID 37258521, 2023). "In addition, 11 tumor-specific exonic variants were identified in six genes spanning the 8p11-p12 genomic region (RAB11FIP1, GPR124, ADAM2, LSM1, TACC1, ZNF703)." (PMID 29844878, 2018). "In mouse tumor models, we could show that Adam2 expression is induced in KrasG12D but not BrafV600E tumors and its expression is further increased upon immunotherapy, indicating that Adam2 is an oncogene- and immune-responsive bona fide cancer-testis antigen." (PMID 37258521, 2023). "ADAM2 also restricts expression of the immune checkpoint inhibitors PDL1, LAG3, TIGIT and TIM3 in the tumor microenvironment, which might explain why ex vivo expanded and adoptively transferred cytotoxic T-cells show enhanced cytotoxic efficacy in ADAM2 overexpressing tumors." (PMID 37258521, 2023). "To further study the function of Adam2 during tumor development and immune regulation, we overexpressed Adam2 together with the OVA-peptide SIINFEKL in LLC1 cells (=Adam2 O/E cells)." (PMID 37258521, 2023). "In addition, although ACT treatment significantly reduced the tumor burden in control lungs, it did not have a significant therapeutic effect in sgAdam2-deficient lungs—in fact there was a trend towards increased growth of treated Adam2-deficient tumors." (PMID 37258521, 2023). "On the other hand, within these functional classes, we have also observed over-expression of metalloproteases (i.e., ADAM2) or ECM metalloproteases inducers (i.e., BSG) typically induced by several tumor cells." (PMID 29559981, 2018).
tumor (continued). "Since forced expression of Adam2 had no impact on tumor growth or survival in immunodeficient hosts, these data indicate that Adam2 suppresses endogenous immune responses that restrain the growth of LLC cells." (PMID 37258521, 2023). "Indeed, immunohistochemistry identified significantly increased infiltration of CD8 T cells in treated Adam2 knockout tumors but with a concomitant drastic increase expression of the PDL1 exhaustion marker, indicating an immune-suppressive tumor environment." (PMID 37258521, 2023). "PDL1 as well as CTLA4 blocking Ab significant slowed tumor growth of Adam2 O/E tumors, while control tumors showed little or no reduction in growth." (PMID 37258521, 2023).
cancer (5 papers, 2008 to 2023). A tumor composed of atypical neoplastic, often pleomorphic cells that invade other tissues. "We also unveil the role of a poorly characterized cancer-testis antigen, Adam2, in establishing a cold TME by blocking type I and II interferon and TNFα pathways." (PMID 37258521, 2023). "To extend our findings from mouse to human cancer, we performed pan-cancer analysis for ADAM2 from The Cancer Genome Atlas (TCGA)." (PMID 37258521, 2023). "Pan-cancer analysis for ADAM2 showed a high frequency of expression in breast (9.5%), lung (9.6%), bladder (16.7%), prostate (72.4%) and renal (74.7%) cancers." (PMID 37258521, 2023). "They recovered the known immune evasion factors Stat1 and Serpin Family B Member 9 (Serpinb9) and identified the cancer testis antigen ADAM Metallopeptidase Domain 2 (Adam2) as an immune modulator, whose expression is induced by KrasG12D and further elevated by immunotherapy." (PMID 38162677, 2023).
ADAM2 also shares sentences with these, for which no sentence is quoted: infection (2 papers); Infertility (1); melanoma (1); testicular cancer (1).